VPS13B (vacuolar protein sorting 13 homolog B)
Diseases named in the same sentence as VPS13B in open-access papers (continued):
Sharing a sentence is not in itself a finding about the gene and the disease.
Cohen syndrome (continued). "Mental retardation observed in Cohen syndrome suggests that VPS13B plays a role in brain development or maintaining brain function in humans." (PMID 21605373, 2011). "Dogs affected with TNS are the first animal model for Cohen syndrome and can be used to study the development of the disease and the effect at the cellular level of varying expression of VPS13B." (PMID 21605373, 2011). "The patient did however not display typical clinical features of Cohen syndrome associated with autosomal recessive VPS13B deficiency." (PMID 35870028, 2022). "While 22 different VPS13B pathogenic genetic variants were identified in patients having “Cohen syndrome”, no VPS13B pathogenic variants were identified in patients who only had “Cohen-like syndrome”." (PMID 30473963, 2018). "However, a systematic pathogenicity assessment of these VPS13B missense variants has not been performed and their role for Cohen syndrome or other entities is difficult to interpret." (PMID 35690661, 2022). "Alterations of vacuolar protein sorting‐associated protein 13 (VPS13) family members including VPS13A, VPS13B, and VPS13C lead to chorea acanthocytosis, Cohen syndrome, and parkinsonism, respectively." (PMID 31876103, 2020). "The strong similarity in clinical signs between Cohen syndrome and TNS is supporting evidence that VPS13B is the TNS gene." (PMID 21605373, 2011). "Functional studies have shown that the increased fat accumulation in patients with Cohen syndrome is due to an increased propensity of pre-adipocytes lacking the VPS13B protein to differentiate into fat-storing cells." (PMID 36232301, 2022). "The molecular mechanism of Cohen syndrome is not known yet while the function of VPS13B in tethering of endosomes and autophagy in neuronal cells are recently reported." (PMID 36153334, 2022). "It is also able to detect the N-tetrasaccharide for ALG1-CDG diagnosis and highly abundant abnormal high mannose species of 3 Man- and 4 Man-glycans in PMM2-CDG and MPI-CDG, and to show abnormal profiles for tissue-specific glycosylation defects for VPS13B-CDG, also called Cohen syndrome." (PMID 29497882, 2018). "Functional studies have shown that the increased fat accumulation in patients with Cohen syndrome is due to an increased propensity of pre-adipocytes lacking VPS13B to differentiate into fat-storing cells." (PMID 30473963, 2018). "Together, these results show that VPS13B is involved in intracellular trafficking of CXADR as well as the barrier function of human gingival epithelial tissues, and thus indicate the molecular basis for periodontal complications in patients affected by Cohen syndrome." (PMID 41730960, 2026).
microcephaly (14 papers, 2014 to 2026). A congenital or acquired developmental disorder in which the circumference of the head is smaller than normal for the person's age and sex. "Disruption of VPS13B causes autosomal recessive Cohen syndrome, a rare disorder characterized by microcephaly and intellectual disability, along with other features including hypotonia." (PMID 41522673, 2026). "Live phenotype analyses together with Sudan black B staining showed that the three critical clinical symptoms of CS, microcephaly, ocular defects, and neutropenia, are present in Vps13b-depleted zebrafish embryos." (PMID 41522673, 2026). "Deleting VPS13B in human pluripotent stem cells (hPSCs) resulted in Golgi dispersion in hPSCs and a slow onset of growth retardation in mutant hANOs, akin to CS patients with postnatal microcephaly." (PMID 41522673, 2026). "Moreover, a homozygous frameshift mutation in VPS13B was found in an ASD case with mild dysmorphic features and microcephaly." (PMID 36153334, 2022). "Using a constitutive Vps13b knockout mouse, we found that about half of homozygous pups die in the first postnatal week and that survivors display core features of the human disorder: postnatal microcephaly, altered memory, hypotonia, growth delay, and increased sociability." (PMID 41522673, 2026). "Variants in multiple genes regulating endosomal trafficking and/or fusion of secretory vesicles [such as SMPD4, WDFY3, TRAPPC4, RAB18, VPS13B, EXOC7, EXOC8, VPS11], have been associated with the occurrence of microcephaly, cerebral atrophy, and neurodevelopmental delay." (PMID 36538041, 2023).
Intellectual disability (13 papers, 2014 to 2026). "There is a clinical overlap between NAPB- and VPS13B-associated neurodevelopmental features of intellectual disability, developmental delay, and autistic spectrum; however, the EOEE characterizes the NAPB phenotype." (PMID 36780047, 2023). "Furthermore, VPS13B mutations have been found in individuals with autism and non-syndromic intellectual disability." (PMID 25502226, 2014). "VPS13B is indispensable for the Golgi apparatus, and genes important for Golgi morphology and function have been linked to autism disorders, including RAB39B, mutated in a X-linked intellectual disability associated with autism, epilepsy and macrocephaly, and UBE3A, responsible of Angelman syndrome." (PMID 25502226, 2014).
autism (7 papers, 2014 to 2023). Persistent deficits in social interaction and communication and interaction as well as a markedly restricted repertoire of activity and interest as well as repetitive patterns of behavior. "Whole exome sequencing of the parents and their monozygotic triplets, part of a Qatari cohort recruited for an autism genetics study, identified two genetic variants of potential interest: a missense mutation in VPS13B, c.8516G>A 9 (p.Arg2839Gln); and a splice site loss variant in NAPB, c.354+2T>G." (PMID 38260021, 2023). "Significantly greater than expected number of rare variants were detected in 5 of the 101 tested autism-linked genes: AUTS2, NHS, NSD1, SLC9A9, and VPS13B." (PMID 31134136, 2019).
neutropenia (7 papers, 2011 to 2026). A decrease in the number of neutrophils found in the blood. "We speculated that the de novo event p.Tyr3434* dominated the missense variant p.Arg237Pro in Patient 1, resulting in a complete VPS13B LoF and, consequently, a CS phenotype that includes neutropenia." (PMID 39723426, 2024).
chorea-acanthocytosis (6 papers, 2016 to 2023). Chorea-acanthocytosis (ChAc) is a form of neuroacanthocytosis and is characterized clinically by a Huntington disease-like phenotype with progressive neurological symptoms including movement disorders, psychiatric manifestations and cognitive disturbances. "Mutations in VPS13A and VPS13B cause the genetic diseases chorea-acanthocytosis (ChAc) and Cohen syndrome, respectively, and a loss of VPS13C function has recently been linked to early-onset Parkinson's disease." (PMID 27329800, 2016). "There are four human homologs (VPS13A–D), and mutations in these genes result in chorea-acanthocytosis (ChAc) (VPS13A), Cohen’s syndrome (VPS13B), early-onset parkinsonism (VPS13C) and childhood-onset movement disorder (VPS13D)." (PMID 33668157, 2021). "Humans express four different VPS13 paralogs, designated A through D. Mutations in VPS13A, VPS13B, VPS13C and VPS13D are associated with the neurodegenerative disorder Chorea-Acanthocytosis (ChAc), Cohen Syndrome, Parkinson’s Disease, and a form of cerebellar ataxia, respectively." (PMID 34201352, 2021).
Obesity (5 papers, 2019 to 2025). Accumulation of substantial excess body fat. "Of them, Ctnnd2, Dap, Marchf6, Cmbl, Sdc2, Cpq, Stk3, Vps13b, Cox6c, Grhl2, Fzd6, Cthrc1, Lrp12, and Zfpm2 showed associations or had functions related to atherosclerosis or obesity." (PMID 40362477, 2025). "In summary, the obtained results suggest that regions 8q22-24, 11q23-25, and 12q13-15 are very likely to contain genes like VPS13B, APOA5, ZPR1, BUD13, and FAIM2 that control obesity-related factors in Iranian families with MetS21,22,27,28,31,32." (PMID 33727680, 2021).
congenital neutropenia (4 papers, 2020 to 2025). "Genetic variants in G6PC3, JAGN1, and VPS13B affect the number and function of neutrophils (rather than their migration) which consequently cause different forms of severe congenital neutropenia (SCN)." (PMID 38550576, 2024).
schizophrenia (3 papers, 2015 to 2024). A major psychotic disorder characterized by abnormalities in the perception or expression of reality. "Prior genetic studies linked 16p13.11 duplication and VPS13B deletion to schizophrenia and mental disorders." (PMID 38439002, 2024). "As outlined in S11 Table, seven of these genes have, to varying degrees, plausible links to cognition (i.e. DGKB, NPS, VPS13B, RBM20, ABHD4, ESRRB, and DOPEY2), with some active in systems implicated in schizophrenia pathology (NPS, DGKB, ABHD4, ESRRB)." (PMID 25860228, 2015).
atherosclerosis (2 papers, 2022 to 2025). A disease characterized by the build-up of fatty material and calcium deposition in the arterial wall resulting in partial or complete occlusion of the arterial lumen. "VPS13B participates in the pathoevolution of atherosclerosis-induced IS." (PMID 35754821, 2022).
autism spectrum disorder (2 papers, 2020 to 2024). A spectrum of developmental disorders that includes autism, and Asperger syndrome. "VPS13B missense variants have also been linked to autism spectrum disorders (ASDs), as noted in a previous study." (PMID 39723426, 2024).
breast carcinoma (2 papers, 2015 to 2025). "The somatic mutation patterns of ERGs in breast cancer highlighted APOB, LRP1, and VPS13B as the top 3 frequently mutated genes." (PMID 39792732, 2025).
depression (1 paper, 2025). "Six potential depression‐related target genes of miR‐511‐3p were identified: CXCR4, LBR, CPS1, VPS13B, COL9A3, and GABRB3." (PMID 41341504, 2025).
diabetes (1 paper, 2024). "Dysregulated insulin response due to defective VPS13B may explain the occurrence of diabetes in some CS patients." (PMID 38439002, 2024).
dysplasia (1 paper, 2014). A usually neoplastic transformation of the cell, associated with altered architectural tissue patterns. "Together with the fact that VPS13B does not fit well to her severe hematologic findings and bone marrow dysplasia, FLAGS helped us select SENP1 as candidate gene for our experimental validation studies." (PMID 25466818, 2014).
invasive breast carcinoma (1 paper, 2024). A carcinoma that infiltrates the breast parenchyma. "In investigations concerning primary invasive breast cancer, aberrant methylation and transcription patterns of VPS13B have been implicated in the promotion of tumor suppressor gene inactivation or oncogene activation." (PMID 39103807, 2024).
McLeod syndrome (1 paper, 2025). "In some patients with McLeod syndrome due to large deletions, VPS13B and DMD may be lost." (PMID 41190063, 2025).
melanoma (1 paper, 2015). A malignant, usually aggressive tumor composed of atypical, neoplastic melanocytes. "As anticipated, the copy number of the host gene of miR-599 VPS13B is similarly reduced in melanoma cells and fresh melanoma isolates with low levels of miR-599." (PMID 26573229, 2015). "Whether reduction in copy number of the genes encoding for the miRs are due to genomic variations at extended fragments of chromosome remains to be determined, but the copy number of VPS13B is similarly reduced in melanoma cell lines and fresh isolates with low levels of miR-599." (PMID 26573229, 2015).
myelodysplastic syndrome (1 paper, 2025). A clonal hematopoietic disorder characterized by dysplasia and ineffective hematopoiesis in one or more of the hematopoietic cell lines. "Overall, 16 patients (17.2%) had pathogenic variants, including FANCA, BRCA2, PMS2, ELANE, G6PC3 and VPS13B in patients with idiopathic neutropenia, and GATA2 in patients with suspected myelodysplastic syndrome." (PMID 40358701, 2025).
neuropathies (1 paper, 2020). "At least TUBGCP6, SYNE1, BPTF, KIDINS220, MYO5A, VPS13B, TBC1D24) are known to contain mutations causing various neuropathies." (PMID 32561887, 2020).
ovarian carcinoma (1 paper, 2024). A malignant neoplasm originating from the surface ovarian epithelium. "VPS13B, TBC1D22A, PPP3CA, CUX1 and PPP1R15A were identified as poor prognostic genes for cisplatin resistance in ovarian cancer, while PLGRKT, CDKAL1 and TAP1 were identified as good prognostic genes." (PMID 39103807, 2024). "Through biological information screening, RT-qPCR and WB verification, it was found that VPS13B, TBC1D22A, PPP3CA, CUX1 and PPP1R15A were highly expressed in cisplatin-resistant tissues of ovarian cancer, while PLGRKT, CDKAL1 and TAP1 were low expressed." (PMID 39103807, 2024). "VPS13B, TBC1D22A, PPP3CA, CUX1 and PPP1R15A were identified as poor prognostic genes of cisplatin resistance in ovarian cancer, while PLGRKT, CDKAL1 and TAP1 were identified as good prognostic genes." (PMID 39103807, 2024). "The expression levels of VPS13B, TBC1D22A, PPP3CA, CUX1, and PPP1R15A genes were found to be up-regulated in ovarian tissue of cisplatin-resistant ovarian cancer patients compared to those with ovarian cancer." (PMID 39103807, 2024).
neurological disorders (5 papers, 2017 to 2024). "There are four members of the Vps13 family—Vps13a, Vps13b, Vps13c, and Vps13d—and mutations in each gene cause distinct neurological diseases." (PMID 39063018, 2024).
tumor (5 papers, 2015 to 2024). "Vice versa, despite a relatively high AF, only two mutations were exclusively detected in tumor biopsies (VPS13B (vacuolar protein sorting 13 homolog B), AF 0.09, Pat ID 1385 and APC, AF 0.2, Pat ID 1364), compared to 15 and 6 mutations that were detected only in plasma or stool, respectively." (PMID 38766867, 2024). "Tumor cells with BRAFV600E mutation from PT and LM all highly expressed VPS13B, a gene that may function in vesicle-mediated transport, and L3MBTL2, a gene that may inhibit cell divisions." (PMID 35974387, 2022).
cancer (2 papers, 2019 to 2024). A tumor composed of atypical neoplastic, often pleomorphic cells that invade other tissues. "Nonetheless, exosomal proteins previously reported to be associated with vesicle secretion in cancer cell line supernatants (RAP1A, RAP1B, VAMP1, MYH7, MYO18a, MYOLPF, MYO1E, VPS13B, HSP70) were identified in our samples." (PMID 30764491, 2019).
hematopoietic diseases (1 paper, 2025). "Heterozygous P/LP variants in genes associated with other hematopoietic diseases or developmental disorders with autosomal recessive inheritance were identified in ADAMTS13, GBA1 (n=3), and VPS13B." (PMID 40766138, 2025).
neurodegenerative disease (1 paper, 2022). A disorder of the central nervous system characterized by gradual and progressive loss of neural tissue and neurologic function. "The ‘Human UP’ genes include FOXP2, MTRNR2L8, DHX40, VPS13B, WDFY2 and PURB, all of which are associated with neurodevelopment or neurodegenerative disease." (PMID 36052683, 2022).
VPS13B also shares sentences with these, for which no sentence is quoted: developmental delay (6 papers); infection (5); neurodevelopmental disorder (5); meningitis (4); Truncal obesity (4); myopia (3); autosomal recessive deafness (2); epilepsy (2); fragile X syndrome (2); genetic disorder (2); Macrocephaly (2); Parkinson disease (2); Parkinsonism (2); Prader-Willi syndrome (2); prostate carcinoma (2); Retinal dystrophy (2); Sepsis (2); Alstrom syndrome (1); Angelman syndrome (1); anhidrosis (1); Arrhythmogenic right ventricular dysplasia (1); autosomal dominant deafness (1); bacteremia (1); Bardet-Biedl syndrome (1); beta thalassemia (1); Birk-Barel syndrome (1); bladder infection (1); Bloom syndrome (1); Borjeson-Forssman-Lehmann syndrome (1); cardiovascular disease (1).
A further 32 diseases each share a sentence with VPS13B in 1 paper.